SNORD98 (small nucleolar RNA, C/D box 98)
Synonyms: HBII-419
Gene: Small nucleolar RNA gene on chromosome 10 (68,755,172 to 68,755,238, forward strand). Ensembl gene ENSG00000283551.
Gene Ontology:
Biological process: RNA processing
Cellular component: nucleolus
Homologues: Orthologues: macaque SNORD98 (100% identical), guinea pig SNORD98 (96% identical), mouse Snord98 (96% identical), pig SNORD98 (96% identical), rabbit SNORD98 (96% identical), dog SNORD98 (94% identical), rat Snord98 (94% identical).
Diseases named in the same sentence as SNORD98 in open-access papers:
SNORD98 is named in the same sentence as 1 disease in open-access papers, as found by Europe PMC text mining. Sharing a sentence is not in itself a finding about the gene and the disease.
SNORD98 shares sentences with these, for which no sentence is quoted: tumours (1 paper).